SOCS1 (suppressor of cytokine signaling 1)
Diseases named in the same sentence as SOCS1 in open-access papers (continued):
Sharing a sentence is not in itself a finding about the gene and the disease.
viral infection (43 papers, 2008 to 2025). "Suppressor of cytokine signaling 1 (SOCS-1) is implicated in both virus infection and carcinogenesis." (PMID 35733955, 2022). "Together these findings, we propose that impaired antiviral response of IFN-λ due to the inhibitory effect of SOCS-1 causes an adaptive increase in IFN-λ expression by host to protect cells against the viral infection." (PMID 24391501, 2014). "Together, these data imply that suppression of IFN-λ signaling by virus-induced SOCS-1 causes an adaptive increase in IFN-λ expression by host to protect cells against the viral infection, as a consequence, leading to excessive production of IFN-λ with impaired antiviral response." (PMID 24391501, 2014). "Although not investigated directly, our data suggest that genetic polymorphisms in either the TGFΒ2 or SOCS-1 gene may dictate varying degrees of susceptibility to virus infection in asthma." (PMID 22970254, 2012). "During viral infection, the SOCS1 gene is regulated by sixteen miRNAs, including the let-7 family, miR-98-5p, miR-122-5p, miR-222-3p, miR-4266, miR-4458, miR-4500, miR-4695-5p, miR-4779, and others." (PMID 41155393, 2025). "For example, miR‐155, known to be upregulated in severe viral infections, targets SOCS1 and promotes inflammatory signaling." (PMID 40844207, 2025). "SOCS1 negatively regulates interferon signalling, which can reduce the ability of the body to clear viral infections." (PMID 40670973, 2025). "SOCS1/3 antagonists have shown promise in treating viral infections, including HSV-1, Influenza A, and vaccinia virus infections, both in vitro and in mice." (PMID 38711523, 2024). "This process results in a reduction of antiviral immune responses, highlighting SOCS1 as a potential therapeutic target for virus infections." (PMID 38711523, 2024). "Studies in larger patient cohorts are needed to understand the impact of miRNA-155 and SOCS1 interaction on the progression of viral infections." (PMID 36380817, 2023). "Studies in larger patient cohorts are needed to understand the effect of MiR-155 and SOCS1 interaction on the progression of viral infections." (PMID 35885930, 2022). "An important finding of the current and previous studies is that SOCS proteins are upregulated following viral infection; expression of SOCS1 or SOCS3 following viral infection promotes the replication of multiple viruses." (PMID 35774982, 2022). "Manipulation of SOCS1 and SOCS3 should play a key role in viral infections, particularly those caused by viruses that are associated with respiratory diseases." (PMID 33193390, 2020). "The first use of SOCS1/3 antagonist in a virus infection involved the double-stranded DNA virus, herpes simplex virus (HSV-1)." (PMID 33193390, 2020). "Targeting of Socs1 by miR-155 has also been shown to disrupt T cell function in response to viral infection, and these studies emphasized the importance of both cell type and context in determining how miR-155 affects lymphocyte function." (PMID 27604627, 2016). "When PBECs from asthmatic subjects were treated with anti-TGF-β antibodies prior to virus infection, both SOCS-1 and SOCS-3 mRNA were significantly reduced at 48 h p.i., p = 0.031 and p = 0.016 respectively." (PMID 22970254, 2012). "SOCS1 is induced during virus infection and binds directly to the type I IFN and/or II IFN receptors to suppress IFN signaling, thereby preventing chronic inflammation." (PMID 21079688, 2010). "RSV and RSV mutant virus infection of MLE-15 cells at 24 h pi was associated with IFNα, IFNβ and SOCS1 and SOCS3 mRNA expression." (PMID 18851747, 2008). "Furthermore, during viral infection, upregulation of SOCS1—a key negative regulator of the JAK/STAT signaling pathway—typically serves as a host feedback mechanism to prevent excessive inflammation." (PMID 41009378, 2025).
viral infection (continued). "It was also demonstrated that while SOCS1−/− mice experienced higher levels of TNFα, IL-10, and IL-17 compared to wild-type mice, in the context of viral infections, SOCS1 overexpression could decrease the concentrations of virally induced TNFα." (PMID 39867889, 2024). "In addition, miR-155 expression induced by viral infection targets SOCS1 (a STAT inhibitor) to inhibit SOCS1 activity and generates feedback to promote IFN-I-mediated antiviral activity." (PMID 36560611, 2022). "Since SOCS-1 is related to both viral infection and carcinogenesis, SOCS-1 may be involved in HCV-induced hepatocarcinogenesis." (PMID 35733955, 2022). "SOCS1 ablated cells and SOCS1−/− mice are resistant to viral infection." (PMID 33072096, 2020). "Additional in vitro experiments may be used to elucidate the proposed SOCS1 induction by PRRSV during the initial phase of virus infection." (PMID 25889072, 2015). "We show here that the SOCS1 mimetics are effective in treatment of autoimmune and inflammatory disorders and that the SOCS1 antagonists enhance the immune response for effective handling of viral infections by tilting immune homeostasis toward increased immune activity." (PMID 25954276, 2015). "Our hypothesis is that suppression of cytokine signaling by virus-induced SOCS-1 leads to an adaptive increase in IFN-λ production by host to protect cells against viral infection." (PMID 24391501, 2014). "SOCS1 can also be induced during virus infection and plays a positive role in viral replication." (PMID 21079688, 2010). "Therefore, we propose that miR-19a/b may upregulate JAK/STAT signal transduction by suppressing SOCS1 expression, leading to inhibition of viral infection." (PMID 38435118, 2024). "SOCS1 and SOCS3 are increasingly recognized as central regulators of host immune responses during viral infections." (PMID 40844207, 2025). "The antagonist, pJAK2 (1001‐1013), is a SOCS1 and SOCS3 inhibitor that binds to the KIR region, blocking their inhibitory activity in different viral infections, such as HSV‐1 and influenza A." (PMID 40844207, 2025). "SOCS1 mimetic peptides have also been suggested in the context of SARS-CoV-2 and other viral infections." (PMID 38711523, 2024). "The Mechanism of CMV Infection), the involvement of SOCS1 and SOCS3 in the signaling pathway during viral infection is well-documented." (PMID 39066272, 2024). "The influence of EGb on inflammatory-associated genes expression that regulate innate immune response to viral infection and cytokine production, namely IRF-3, IRF-7, tetherin, SOCS1, SOCS3, NFKB1, p65, and MxA was also examined." (PMID 35631163, 2022). "SOCS1 and SOCS3 mRNA levels were increased in the early stage of viral infection, accompanied with increased mRNA levels of IFNα and IFNβ." (PMID 32149091, 2020). "During Zika virus (ZIKV) infection, Axl regulates the expression of SOCS1 in a STAT1/STAT2-dependent manner, thereby antagonizing IFN-I-mediated antiviral immunity, promoting virus infection and replication." (PMID 33072096, 2020). "In our study, SOCS1 and SOCS3 were increased in the early stage of viral infection in RD cells infected with an increased titer of EV71, accompanied by increased IFNα and IFNβ." (PMID 32149091, 2020). "The accumulated data suggests that SOCS1 and/or SOCS3 can differentially affect the severity of viral diseases in a highly cell-type-specific manner, reflecting the diversity and complexity of herpesvirus infection and the ocular compartment." (PMID 31031749, 2019). "Hsa-miR-150-5p was linked to the greatest number of mRNA targets (sixteen), including SOCS1, SAMD4A, and IFIT5, which were part of previously published gene expression signatures for viral infection." (PMID 30619110, 2018). "Growing evidence suggests that SOCS1 and SOCS3 are important inhibitory modulators in limiting the inflammatory effect of interferon signaling during viral infection." (PMID 21901105, 2011).
viral infection (continued). "Suppressor of cytokine signaling 1 (SOCS1) belongs to the SOCS protein family and is induced after virus infection." (PMID 21079688, 2010). "This is not unexpected because SOCS proteins form part of a classical negative feedback loop that is time-dependent, thus RSV and RSV mutant virus infection of MLE-15 cells and IFNα, IFNβ and SOCS1 and SOCS3 mRNA expression was examined at 48 h pi." (PMID 18851747, 2008). "Previous studies have theorized that hsa-miR-146a is overexpressed in many viral diseases, targeting and inhibiting specific genes, such as STAT1, SOCS1/STAT3, TCL1, CXCL4, and NFκB in hepatitis B and C, EBV, human immunodeficiency type-1, and human T-lymphotropic type 1, respectively." (PMID 37233676, 2023). "Accumulated data indicate that SOCS1 and/or SOCS3 may have different effects on the severity of viral diseases depending on the type of cells." (PMID 36032295, 2022). "We knocked down SOCS1 and SOCS3 via shRNA in RD cells prior to viral infection." (PMID 32149091, 2020). "Additionally, our results revealed that miR-221-5p activated the NF-κB pathway by targeting NFKBIA and SOCS1, inhibitors of NF-κB signaling and mediators of IFN and ISG production, to inhibit viral infection." (PMID 30380612, 2018). "It is possible to observe a process of evasion of the immune response, most likely mediated by viral infection, showing a decrease in the transcription of evaluated ISGs in DENV-2 infected cells compared with cells stimulated with IFN-λ and an increase in SOCS1 and SOCS3 genes." (PMID 26411318, 2015). "However, it is interesting to note that SOCS1 is also strongly targeted by miR-155, a miRNA induced by Toll-like receptors, RIG-I and viral infection." (PMID 23894411, 2013). "Comparing time-points post-WT or ΔG virus infection, no significant (p < 0.05) changes in IFNα, IFNβ or SOCS1 mRNA expression were observed at 24 h pi or 48 h pi; however, SOCS3 mRNA expression was considerably decreased from 24 h pi to 48 h pi." (PMID 18851747, 2008). "This suggests that SOCS1 expression, when introduced as a transgene in an oncolytic HSV-1 vector, may facilitate viral replication and oncolysis in cells that typically resist viral infection." (PMID 39850819, 2024). "SOCS1 and SOCS3 may promote virus infection by inhibiting IFN-induced STAT3 phosphorylation." (PMID 32149091, 2020). "RSV and RSV mutant virus infection of MLE-15 cells induced different type I IFN and SOCS1 and SOCS3 mRNA expression patterns at 24 h and 48 h pi, a feature that may be linked to sequential RSV gene expression due to their promoter-proximal location in the genome." (PMID 18851747, 2008).
Insulin resistance (35 papers, 2008 to 2025). Increased resistance towards insulin, that is, diminished effectiveness of insulin in reducing blood glucose levels. "Of note, the mutation in the promoter region of the SOCS1 gene (rs243330, −1656G>A) was associated with obesity and insulin resistance in the general population." (PMID 31717271, 2019). "The cellular mechanisms of acromegaly-associated insulin resistance involve direct GH-mediated expression of suppressors of cytokine signaling (SOCS-1/-6) or indirect activation of nutrient-sensing pathways due to excessive lipolysis and proteolysis." (PMID 19093000, 2008). "It seems that the presence of homozygous GG variants of the SOCS1 gene may be protective from the presentation of insulin resistance, but only in the early stages of hepatic steatosis since this difference disappears in the group of obese NAFLD." (PMID 31717271, 2019). "Also, SOCS1 has been shown to down-regulate insulin signaling and cause insulin resistance." (PMID 36609306, 2023). "Furthermore, SOCS1 gene promoter mutation is related to obesity and insulin resistance." (PMID 36609306, 2023). "Our study revealed that siRNA SOCS1 reversed the inhibitory effects of miR-221-3p inhibition on PA-induced insulin resistance in 3T3-L1 cells." (PMID 41002956, 2025). "This suggests that the excessive activation of miR-221-3p contributes to chronic inflammation and insulin resistance in skeletal muscle, likely through the dysregulation of SOCS1 and overactivation of the JAK/STAT pathway." (PMID 40070461, 2025). "They found that the expression of SOCS1 was significantly decreased in insulin-resistant subjects, suggesting a potential role for SOCS1 in the development of insulin resistance and type 2 diabetes." (PMID 38874740, 2024). "The intersected genes between DEG- and DMR-targeted genes were gathered in type II diabetes mellitus, insulin resistance, and metabolic pathways, which referred to Nos3, Pik3r1, Socs1, and Acly." (PMID 37287451, 2023). "In another study, adenoviral-mediated expression of SOCS1 in mouse liver blocked insulin signaling by ubiquitin-mediated degradation of insulin receptor substrates 1 and 2, resulting in insulin resistance." (PMID 36609306, 2023). "MiR-155 was implicated in osteogenesis inhibition through the regulation of SMAD5, and SOCS1 expression was detected in exosomes derived from obese adipose tissue and promoted insulin resistance." (PMID 36831188, 2023). "A total of 92 genes were intersected between DEGs and DMRs-targeted genes, of which Nos3, Pik3r1, Socs1, and Acly were gathered in type II diabetes mellitus, insulin resistance, and metabolic pathways." (PMID 37287451, 2023). "There are studies that have reported that Aβ induces hepatic insulin resistance by activating JAK2/STAT3/SOCS-1 signaling pathway and have implications on resolving insulin resistance and T2DM." (PMID 34991691, 2022). "Amyloid-β protein can lead to insulin resistance as well as the development of T2DM through the activation of the JAK2/STAT3/SOCS1 pathway." (PMID 34991691, 2022). "It has been reported that SOCS-1 and SOCS3 are associated with insulin resistance in various cells through degradation of IRS-1 and IRS-2." (PMID 34416903, 2021). "IL-6 has been shown to activate SOCS-1 and -3 proteins in the liver, thus accompanying insulin resistance." (PMID 32047529, 2020). "Cebpb, Hdac4, Ski, Socs1 mRNAs, which are reduced in diabetes and/or insulin resistance, have also demonstrated protective roles in these conditions." (PMID 30369883, 2018). "Since SOCS1 and SOCS3 have been implicated in the development of leptin and insulin resistance, we further evaluated the mRNA expression level of these genes." (PMID 29025435, 2017). "Chronic activation of STAT3 has been reported to play a part in the development of insulin resistance by increasing the levels of SOCS1 and SOCS3 proteins." (PMID 28783714, 2017).
Insulin resistance (continued). "Macrophage accumulation in the liver and liver inflammation resulted in hepatic insulin resistance in these animals, highlighting the role of SOCS1 in restraining M1 inflammatory responses, while promoting M2 macrophage polarization." (PMID 26579124, 2015). "SOCS-1 is involved in inflammatory response and insulin resistance." (PMID 40572705, 2025). "Moreover, increased SOCS1 levels in cultured muscle cells and adipocytes can lead to insulin resistance via the inhibition of tyrosine phosphorylation of insulin receptor substrate proteins and subsequent downstream signaling." (PMID 36609306, 2023). "Moreover, mRNA expression of SOCS1 and SOCS3 in SAT was associated with known obesity indices, insulin resistance, and hs-CRP, suggesting the contribution of SOCS1 and SOCS3 in the pathogenesis of obesity-related metabolic abnormalities." (PMID 36609306, 2023). "Moreover, they found that SOCS1 and SOCS3 inhibit insulin signaling and cause insulin resistance by inhibiting insulin receptor substrate 1 (IRS1) and IRS2 binding to the insulin receptor in cultured L6 myotubes and 3T3L1 adipocytes." (PMID 36609306, 2023). "Furthermore, elevated SOCS1 in obese individuals increased adipose tissue macrophage response to endotoxin, downstream pro-inflammatory cytokine production, and insulin resistance." (PMID 36437471, 2022). "Hepatic expression of SOCS1 is elevated in rodent models of obesity and insulin resistance, and adenoviral-mediated SOCS1 gene transfer into the mouse liver resulted in glucose intolerance and insulin resistance." (PMID 31717271, 2019). "Previous studies show that SOCS1 is suppressed in atherosclerosis but promotes insulin resistance." (PMID 30369883, 2018). "Another condition that may be a candidate for SOCS1-mimetic peptide intervention in macrophages is insulin resistance." (PMID 26579124, 2015). "Conversely, overexpression of SOCS1 could augment hepatic steatosis and insulin resistance." (PMID 39284830, 2024). "In addition, Aβ induced insulin resistance by activating the JAK2/STAT3/SOCS-1 signaling pathway." (PMID 37033452, 2023). "This study showed that despite the role of SOCS proteins in obesity-related insulin resistance, SOCS1 deficiency alone may not be sufficient to alleviate high-fat diet-induced obesity and metabolic complications." (PMID 36609306, 2023). "Over the years the members of the suppressor of cytokine signaling (SOCS) family (mainly SOCS1 and SOCS3) have received the lion’s share of the attention as key players in the development of insulin resistance." (PMID 36609306, 2023). "Wunderlich and others have shown the involvement of SOCS1 and SOCS3 in insulin resistance through the elevation of interleukin-6 (IL-6), thus leading to the activation of the JAK-STAT pathway." (PMID 37529379, 2023). "Over the years, the role of SOCS proteins (mainly SOCS1 and SOCS3) as negative regulators of inflammation has been recognized as crucial to the development of insulin resistance and T2D." (PMID 36078084, 2022). "It has been shown that SOCS1 and SOCS3 are involved in the induction of insulin resistance, and that the ablation of SOCS3 expression in adipose tissue of female mice improves insulin sensitivity to obesity." (PMID 33519913, 2020). "SOCS1 and SOCS3 act as negative regulators in insulin signaling and serve as one of the missing links between insulin resistance and cytokine signaling." (PMID 31717271, 2019). "The upregulation of SOCS1 and SOCS3 has been projected as a mechanism for imparting insulin resistance by the downregulation of IRS1." (PMID 29025435, 2017). "Both SOCS1 and SOCS3 have been attributed to the development of insulin resistance by inhibiting the phosphorylation of IRS1 and IRS2 proteins." (PMID 29025435, 2017). "Next, we analyzed the expression of known negative regulators (i.e., C/EBPβ, HDAC4 and PTEN) of insulin sensitivity and known inducers (i.e., SOCS1 and SOCS3) of insulin resistance." (PMID 27711113, 2016).
Insulin resistance (continued). "It has been shown that there is an increased SOCS-1 expression in insulin-sensitive tissues in obesity and that this inhibits the phosphorylation of IRS-1 and IRS-2, leading to the inhibition of downstream signaling and insulin resistance." (PMID 40572705, 2025). "Analysis of the target genes revealed that CEBPB, but not KRAS, and SOCS1 was upregulated in obese patients MetS and insulin resistance." (PMID 33540559, 2021). "By their ability to promote ubiquitination and proteasomal degradation of insulin receptor substrates 1 and 2 (IRS1, IRS2), which link RTK signaling to PI3K, SOCS1 and SOCS3 can regulate AKT activation in the context of insulin resistance in the liver and other organs." (PMID 32807134, 2020). "Cytokine-induced SOCS1 interacts with the phosphorylated insulin receptor, thereby preventing binding and activation of insulin receptor substrates (IRS), which leads to the inhibition of insulin signaling and the induction of insulin resistance." (PMID 31717271, 2019). "Moreover, inflammation- induced expression of SOCS1 promotes IRS2 ubiquitination, and thus triggers insulin resistance." (PMID 31717271, 2019). "Moreover, increased SOCS1/SOCS3 expression during uveitis induces insulin resistance in neuroretina, and SOCS3 overexpression is responsible for the induction of insulin resistance in mice infected with hepatitis C virus." (PMID 30116482, 2018).